TLR4 (toll like receptor 4)
Diseases named in the same sentence as TLR4 in open-access papers (continued):
Sharing a sentence is not in itself a finding about the gene and the disease.
tumor (continued). "For instance, Salmonella LPS can increase the expression of IL-1β and exert the anti-tumor effect through the inflammasome and the Toll-like receptor 4 (TLR4)-mediated signaling pathway." (PMID 35757741, 2022). "As our initial study revealed that Bcl6 promoted SMMs differentiation via TLR4-initiated pathway, we next sought to address how tumor-derived signals induced TLR4 and subsequent Bcl6 pathway." (PMID 36542153, 2022). "HSP72 and HSP105 on the TEX surface were found to induce DCs to produce increased IL-6 in a TLR2- and TLR4-dependent manner, which in turn promoted tumor invasion by increasing STAT3-dependent matrix metalloproteinases 9 transcription activity in tumor cells." (PMID 35163380, 2022). "TLR4 and TLR7 were the most strongly correlated with tumour stemness features, but TLR9 had an undefined connection with the stemness index in various malignancies, and TLR4, TLR7, and TLR8 were the most associated with the tumour microenvironment." (PMID 35801728, 2022). "As a new anti-tumor protein drug, rhCNB can activate the innate immune system through the TLR4/NF-κB signaling pathway, promote the maturation of dendritic cells, upregulate the expression of macrophages, and induce tumor cell apoptosis." (PMID 36204132, 2022). "HSP70 also mediates the occurrence of tumor-promoting immune microenvironment through TLR4, NF-κB, STAT3, and other signal pathways." (PMID 35957827, 2022). "As such, there are clearly different roles for TLR4 during the development of tumours, compared to response to chemotherapy in our model." (PMID 35962138, 2022). "In particular, tumor cells use TLR4 expressed on their surface to maintain a microenvironment that is conducive to tumor cell survival, thereby evading the body's immune attack." (PMID 35965618, 2022). "We have also shown that the lack of therapeutic effect when BLS is administered at later stages of tumor growth correlates with the decreased expression of TLR4 in the tumor cell surface." (PMID 34321536, 2021). "Several studies have shown that chemotherapy can activate toll-like receptors 4 (TLR4), which exhibited an increase in proinflammatory IL-6 cytokine in blood and organs distant from the primary tumor in animal models and breast cancer patients." (PMID 34572719, 2021). "TLR4 signaling has been shown to enhance the proliferation and migration of malignant tumor cells in patients, and overexpression in tumors was correlated with metastasis and chemoresistance." (PMID 34222016, 2021). "In this context, Yu and colleagues described that platelet–tumor cell interaction through Toll-like receptor 4 (TLR4) promotes tumor metastasis." (PMID 33498251, 2021). "Recent studies show that TLR4 agonists can also break tumor-induced immune tolerance and enhance the innate and adaptive immune responses against cancer." (PMID 33841142, 2021). "The M2 phenotype stimulates tumor initiation, progression, and metastasis by various mechanisms involving TLR4/STAT3, TLR4/TRIF/NF-κB, Wnt/β-catenin, and many other pathways." (PMID 34696292, 2021). "This phenomenon of successful treatment of tumor through activation of TLR4 points to a promising mechanism of anticancer therapeutic strategies." (PMID 34671606, 2021). "TLR4 activation can boost immune system defense against tumor cells through MyD88 which leads to activation or maturation of immune cells such as dendritic cells (DCs), macrophages and T cells." (PMID 34844644, 2021). "Significantly, the increased NOX1 expression in tumor tissues was positively correlated with the expression level of TLR4 and the clinical stages in NSCLC patients." (PMID 34299310, 2021). "A recent study has demonstrated that TLR-4 activation polarized immunotolerant M2 phenotype macrophages to the anti-tumor M1 state and inhibited tumor progression." (PMID 34439380, 2021).
tumor (continued). "At present, a large number of studies have proven that the lipopolysaccharide (LPS)/Toll-like receptor 4 (TLR4) signaling pathway plays an important role in chronic inflammatory diseases and that chronic inflammation is closely related to tumor development." (PMID 33576897, 2021). "HSP70 released by heat-stressed tumor cells induced the production of tumor cell chemokines and activation of dendritic cells via the TLR4 pathway, thus initiating anti-cancer immunity." (PMID 34712697, 2021). "Downregulation of miR-182-5p contributes to inhibition of cell proliferation and promotion of tumor cell apoptosis by impairing the TLR4/NF-κB signaling pathway activity and increasing FBXW7 expression." (PMID 34294040, 2021). "Previously, we showed that TLR4 was highly expressed in tumor tissue of NSCLC patients receiving opioid analgesia, and was correlated with poor outcomes." (PMID 33628591, 2021). "In a model of pancreatic cancer, stimulation of NK cells with the polysaccharide SEP enhanced their cytotoxicity through a TLR4/ Mitogen-Activated Protein Kinase (MAPK)/MAPKs/NF-κB pathway, which was associated with delayed tumor growth." (PMID 33572260, 2021). "We first identified that MDSCs recruited by CXCL10/TLR4 during acute phase inflammation played a critical role in tumor recurrence after liver transplantation through a series of clinical analyses, animal models, and in vitro functional experiments." (PMID 33990548, 2021). "Monocytes, which are present in the PBMC fraction and are sensitive to TLR4 activation, are potentially responsible for the observed improved tumor cell killing." (PMID 34681717, 2021). "High-mobility group box1 (HMGB1) released from tumor cells is an endogenous ligand of platelet toll-like receptor 4 (TLR4)." (PMID 34722319, 2021). "Exposure of the tumor cell supernatants to (toll-like receptor) TLR-2 or TLR-4 (principal receptors of HMGB1) reporter cells, however, did not induce a positive signal in these cells." (PMID 34876407, 2021). "TLR4 overexpression promoted tumor metastasis, recurrence, and drug resistance in pancreatic and colorectal cancers." (PMID 33964962, 2021). "Among the 11 TLRs found, TLR4 is expressed in many kinds of tumor cells, which promotes the development of tumors, especially inflammation-related ones through different signaling pathways, and plays an important role in cancer pain and tumor immune escape." (PMID 34413286, 2021). "Then the higher numbers of apoptotic cells per area of tumor were found in TLR4-mut mice than in WT mice." (PMID 34479599, 2021). "The activation of the TLR4 signaling pathway in tumor cells by LPS can induce tumor proliferation through the COX-2 and EGFR pathways, and can promote metastasis via the NADPH oxidase 1-dependent ROS pathway." (PMID 33628591, 2021). "Subsequently, the molecules in downstream signaling of TLR-4 like AKT and ERK are also involved in the anti-tumor or tumorigenesis effects of TLR-4." (PMID 34904014, 2021). "For example, in a murine pancreatic cancer model, LPS stimulates TLR4 on immune cells in the tumor microenvironment, favoring tumor progression through the NF-κB and MAPK pathways." (PMID 34604233, 2021). "In this study, we first investigated the role of the primary morphine metabolite, M3G, in tumor progression by studying its interaction with tumor-expressed TLR4." (PMID 33628591, 2021). "An elegant study has dissected out a pathway—essential in the study of anti-cancer immunity in mice and humans—whereby HMGB1 that is secreted by dying tumour cells activates TLR4 on dendritic cells." (PMID 34771442, 2021). "Several studies reported that TLR4 agonists have been successfully harnessed as adjuvants in several models of other tumor entities like malignant melanoma and clinically, in BCG immunotherapy." (PMID 34025657, 2021). "A previous study also showed that TLR4 was expressed in the tumor microenvironment, especially in cancer cells." (PMID 34631699, 2021).
tumor (continued). "TLR4 mRNA expression resulted significantly decreased in tumor samples characterized by MLH1 epigenetic silencing (p = 0.0284)." (PMID 34026821, 2021). "During chemotherapy or radiotherapy, DCs require signaling through TLR4 and its adaptor MyD88 for efficient processing and cross-presentation of antigens from dying tumor cells." (PMID 34660305, 2021). "We have shown that TLR4 deficiency inhibited UVB-induced chronic inflammation and reduced immune suppression in tumor microenvironment, resulting in enhanced tumor development." (PMID 34771569, 2021). "Tumor-initiating stem cell-like cells isolated from these mice show tumorigenic activity and self-renewal directed by Toll-like receptor 4 via Nanog stem cell factor’s upregulation." (PMID 34298760, 2021). "In contrast, alcohol ingestion increased tumor incidence in a Toll-like receptor 4-dependent manner." (PMID 34298760, 2021). "More importantly, iTRAQ proteomics data show that knockdown of TLR4 changes the metabolic enzyme profiles in the tumor tissues, which completely abolish the HFD-enhanced ATP production and cancer growth." (PMID 34385421, 2021). "Our results indicate that bacterial activation of TLR4 on innate immune cells in the colon triggers inflammation and promotes tumor growth." (PMID 34025672, 2021). "F. nucleatum also can target tumor cell itself and activate TLR4/MYD88/NF-κB, E-cadherin/β-catenin and other pathways to promote the proliferation of colorectal cancer cells." (PMID 34386004, 2021). "In CT26-bearing mice, PSG-1 induced apoptosis by enhancing the antitumor immune response and activate macrophages through TLR4-dependent signaling pathways to inhibit tumor growth." (PMID 33935714, 2021). "Recently, we have shown that the activation of toll-like receptor 4 (TLR4) of tumor cells induces inflammatory signaling, which influences the composition of exosomes and boosts their immunosuppressive capacity." (PMID 34200790, 2021). "The interplay between HMGB1 and TLR4 contributed to platelet activation and tumor spreading in mice bearing with melanoma and Lewis lung carcinoma." (PMID 34722319, 2021). "To further explore the clinical implications of TLR4, we find that the expression of TLR4 is significantly lower in elderly patients (age >65 years), high pathological grade tumor, higher tumor stage, and progressive tumor." (PMID 34141706, 2021). "Biglycan acts as a DAMP, and here we provided evidence demonstrating that stromal biglycan promotes TNF-α expression in tumor cells through binding to TLR2 or TLR4, and subsequent activation of NF-κB and ERK signaling pathways." (PMID 33966638, 2021). "Given its ability to inhibit the activation of the TLR4-MyD88-NF-κB signaling pathway, the anti-tumor effect of LMWH seems to hold great potential, and its anti-tumor effects deserve further study." (PMID 34867331, 2021). "The activation of TLR4 on multiple immune cells, such as T cells and DCs, represents a powerful means of suppressing tumor growth." (PMID 34900687, 2021). "The CCLE database (n = 1,019) analysis showed that among 21 tumor cell lines, TLR4 gene expression was lowest in salivary glands and highest in the central nervous system." (PMID 34631699, 2021). "We suggest that LMWH also shows great potential anti-tumor effects because of its ability to inhibit the TLR4-MyD88-NF-κB signaling pathway, related to cancer progression and chemotherapeutic drug resistance." (PMID 34867331, 2021). "Independent of the NF‐κB axis, it has been claimed that the excessive expression of TLR4 on tumour cells blocks the cytotoxic effects of T lymphocytes and enhances the growth of the tumour in vivo." (PMID 33336901, 2021). "In this study, we identified TLR4 activation as a mechanism that mediates intestinal inflammation and thereby promotes tumor development." (PMID 34025672, 2021). "MDSCs and CXCL10/TLR4 levels were significantly increased in patients with GWR <60% or tumor recurrence." (PMID 33990548, 2021).
tumor (continued). "We also measured TLR4, MyD88, NF-κB p65, Wnt 1, and β-catenin mRNA and protein expression in the xenograft tumor tissues." (PMID 33849528, 2021). "In the tumor tissue microenvironment, reduced levels of TLR-4 (P = 0.01) were noted along with reduced expression of COX-2 (P = 0.03) in the Anthos group compared with vehicle treatment." (PMID 34926717, 2021). "Gene Set Enrichment Analysis (GSEA) was used to identify the tumor-related pathways that the TLR4 gene was highly expressed in; the expression of the TLR4 gene was verified with the Human Protein Atlas (HPA) database." (PMID 34631699, 2021). "TLR4 triggers immune responses via the TLR4 signaling pathway and promotes tumor development and progression via pro-inflammatory responses." (PMID 34880862, 2021). "In this study, we found that PcrV directly interacts with TLR4 expressed on macrophages, which induces TAM M1 polarization and enhances TAM-mediated killing of tumor cells via the TLR4/MyD88 signaling pathway." (PMID 34900687, 2021). "As LPS is the classic agonist for TLR4, so it is clear that in case of Coley’s toxin the activation of TLR4 through LPS lead to clearance of tumor efficiently." (PMID 34671606, 2021). "To assess the role of host Tlr2 and Tlr4 in Mmp2-OE and Mmp2-KO tumor kinetics, we compared tumor growth in the Tlr2–/–Tlr4–/– DKO mice." (PMID 34032639, 2021). "This is consistent with a report employing pancreatic PCa cells, as well as other cancer cells, which suggested that TLR4/NF-κB activation enhances tumour invasion and metastasis." (PMID 34502140, 2021). "It was pointed out that morphine decreases the ability of natural killer (NK) cells and in particular to induce apoptosis in a target tumor cell line, through both the classical opioid receptor and Toll-like receptor (TLR)-4." (PMID 33757546, 2021). "Recent studies have shown that silica nanoparticles promote the tumor infiltration of CD8+ cytotoxic T lymphocytes (CTLs) by targeting the TLR4/NF-κB pathway." (PMID 34631699, 2021). "In gliomas, the interaction of lipopolysaccharide (LPS) with TLR4 can induce tumor stem cell proliferation, and therapy resistance." (PMID 33588867, 2021). "TLR4 expression in CRC was significantly correlated with tumor stage and cancer-related survival outcomes." (PMID 34479599, 2021). "Immunohistochemical analysis revealed stage-specific expression of TLR4 in the mouse ovarian cycle, and immunofluorescence showed TLR4 expression in the human granulosa-like tumor cell line (KGN)." (PMID 33776924, 2021). "TLR4 activation in the tumour microenvironment further maintains a tumour-favourable inflammatory response and DAMPs expressed by cancer cells can promote angiogenesis." (PMID 34771442, 2021). "It has been shown that LPS promotes tumour invasion through the TLR4‐mediated activation of the NF‐κB pathway, resulting in the up‐regulation of matrix metalloproteinase 2 (MMP2) and the β1‐integrin subunit." (PMID 33336901, 2021). "RFX1 downregulates such pro-tumor factors like Toll-like receptor 4 (TLR4), Interleukin 17A (IL17A), interleukin 5 receptor subunit alpha (IL5RA), and helps in cancer mitigation while being anti-inflammatory." (PMID 33964962, 2021). "Then, TLR4 protein was further validated in 12 pairs of tumor tissues and adjacent normal tissues, eleven patients had higher expression of TLR4 protein in the tumor tissues." (PMID 34718325, 2021). "In mediating the impact of microbes on tumour initiation and development, tumour chemoresistance, chemotherapeutic or immunotherapeutic effectiveness and therapeutic toxicity, TLR4 signalling pathways are concerned." (PMID 34853760, 2021). "The tumor-promoting role of F. nucleatum via activating toll-like receptor 4 (TLR4) signaling pathway has been observed in mice." (PMID 35003221, 2021). "TLR4 is also expressed in multiple cancer cells and its function was mainly centered on the proliferation and invasion, which indicated high TLR4 expression in tumor tissues predicted poor prognosis." (PMID 34718325, 2021).
tumor (continued). "TLR4 is expressed on PCa cells, tumor-infiltrating lymphocytes, and macrophages and has been strongly linked to PCa tumorigenesis and progression including survival, migration, and invasion." (PMID 34959723, 2021). "The addition of LPS causes oxidative damage via ROS production, which results in tumor progression through TLR4 activation." (PMID 34068523, 2021). "Functional TLR4, and the adaptor MyD88, are required for dendritic cells to cross-present antigens from the dying tumour cells and activate tumour-specific T-cell immune response." (PMID 34771442, 2021). "Both poly(I:C), a TLR3 stimulator, and LPS, classical TLR4 stimulator, activated M1 macrophages to produce antitumor nitric oxide (NO) leading to inhibited tumor growth." (PMID 33990205, 2021). "RGD-DMVs were internalized by activated neutrophils and monocytes via the binding of RGD and LPS to integrin αvβ3 and TLR4 respectively, therefore neutrophils and monocytes mediated the transport of DMVs across tumor blood vessels." (PMID 33537088, 2021). "The M1 phenotype is considered pro-inflammatory and anti-tumor, typically acquired after stimulation with GM-CSF, toll-like receptor 4 (TLR4) ligands, and/or IFN-γ." (PMID 32542437, 2021). "Recent studies indicate that TLR4/NF-κB pathway is involved in the progress of several types of tumor." (PMID 34552063, 2021). "Specifically, the combination of TLR4, inflammasome, and IL-12-driven activation induce a response that protects mice from acute tumor progression, metastasis, and recurrence." (PMID 34855754, 2021). "Recent studies showed that in colon tumorigenesis, HA interacts with both CD44 and the abundant TLR4, promoting the growth of tumor grafts in mice." (PMID 34360868, 2021). "TLR4 are also expressed by tumor cells, and the role of the TLR4 signaling pathway in the TME has been reviewed elsewhere." (PMID 33718169, 2021). "The content of serum MMP-2, tumor tissue TLR4, MYD88 were also reduced by Andro treatment with statistical implications (p < 0.05)." (PMID 33967748, 2021). "In this context, MCL was recently reported to interfere with TLR4 signalling in anti-tumour response." (PMID 33803269, 2021). "Our findings indicate that TLR4 signaling can activate ERG transcriptional function in prostate cells via the RAS/MAPK pathway and that pharmacological inhibition of TLR4 can reduce ERG-mediated phenotypes including tumor growth." (PMID 33554122, 2021). "In the microenvironment of cancers, F. nucleatum infection increases M2 macrophage polarization through a TLR4-dependent mechanism to enhance tumor growth." (PMID 34386004, 2021). "Low expression of TLR4 is observed in tumors with malignant performance (high pathological grade, higher tumor stage, and progression)." (PMID 34141706, 2021). "On the other hand, recent studies have demonstrated that the TLR-4 antagonist- resatorvid- blocks solar UV-induced skin tumorigenesis in mice ex-vivo and in-vivo." (PMID 34904014, 2021). "TLR4 can produce trophic factors and vascular growth factors through the TLR4/MyD88/NF-κB signaling pathway and promote tumor proliferation through TLR4/Cyclooxygenase 2 (COX2)/prostaglandin E2 (PGE2)." (PMID 34733783, 2021). "In an effort to improve both acute and long-term tumor protection, we combined the srRNA/mIL12 treatment with our TLR4 agonist GLA-SE, which is a formulated in a squalene-based oil-in-water emulsion." (PMID 34855754, 2021). "Therapeutically, cationic dextran and PEI showed some anti-tumor activity in tumor bearing wild type mice compared to TLR4 knockout mice." (PMID 34988021, 2021). "It is worth noting there is evidence of the role played by tumor-derived neutrophils, which express GrB in antitumor activity mediated by Toll-like receptor 4 agonist." (PMID 33136178, 2021). "High NLRP3, PYCARD and TLR4 expression was found in 31.8% (106/333), 38.6% (129/334) and 35.6% (115/323) of the tumor samples, respectively." (PMID 34540671, 2021).